CAPN5 (calpain 5)
Diseases named in the same sentence as CAPN5 in open-access papers (continued):
Sharing a sentence is not in itself a finding about the gene and the disease.
vitreous hemorrhage (1 paper, 2019). Blood extravasation in the vitreous humor. "Angiogenesis and vitreous hemorrhage are key features of CAPN5-NIV disease and downregulation of opticin may contribute to the increased retinal neovascularization seen in these patients." (PMID 31110225, 2019).
tumor (6 papers, 2017 to 2024). "Importantly, the mutations in CAPN5 and ADAMTSL3 were detected by WES in all four fragments of grade II tumor and were verified by Sanger in all four fragments as well, suggesting that these mutations were likely present in the cell undergoing fast clonal expansion." (PMID 28193203, 2017).
cancer (3 papers, 2019 to 2026). A tumor composed of atypical neoplastic, often pleomorphic cells that invade other tissues. "There is also evidence of Epi-1 modulating different genes in cancer cells, including necrosis related genes (calpain 5 and cathepsin G) and interleukin related genes." (PMID 31824449, 2019).
infection (3 papers, 2018 to 2023). The state of being infected such as from the introduction of a foreign agent such as serum, vaccine, antigenic substance or organism. "In addition, the analysis revealed that some of these proteins had been previously associated to SARS-CoV-2 early (FKBP2; UBXN1; PPP1R11), middle (UBXN1; PPP1R11; CAPN5) and late-stage infection in human male blood (FKBP2; UBXN1; PPP1R11; SURF4; SSU72)." (PMID 37063416, 2023). "To further investigate a possible role of both proteins in fusion and uncoating, we fused HCVcc particles at the plasma membrane of CAPN5 and CBLB knockout cells by low pH wash and monitored infection rates." (PMID 30024968, 2018). "In contrast, CAPN5 and CBLB were necessary for full infection with all tested HCV genotypes, revealing a pan-genotypic requirement for CAPN5 and CBLB." (PMID 30024968, 2018). "CAPN5 and CBLB knockout cells displayed similar infection rates through the plasma membrane bypass, while the HCV fusion inhibitor flunarizine reduced infection rates to background levels." (PMID 30024968, 2018).
neurologic disorders (2 papers, 2012 to 2025). "This study identified several additional CAPN5 targets with potential relevance to retinal neurodegeneration and neurologic disorders." (PMID 40650235, 2025). "Capn5 knockout mice have no observable phenotype, and several human neurological disorders have been associated with excess calpain activity, including photoreceptor degeneration." (PMID 23055945, 2012).
cardiovascular diseases (1 paper, 2007). "As its homologue CAPN10, CAPN5 seems to influence traits related to increased risk for cardiovascular diseases." (PMID 17227582, 2007).
neurodegenerative disease (1 paper, 2017). A disorder of the central nervous system characterized by gradual and progressive loss of neural tissue and neurologic function. "We could also be further exploring adeno associated virus (AAV) delivery CAPN5 scFv as a treatment strategy for CAPN5 mutations-linked ADNIV in eye and activated CAPN5 related-neurodegenerative diseases in central nerve system." (PMID 29245980, 2017). "This may be a possible way to treat of activated-CAPN5 induced photoreceptor cell and neuronal cell degeneration in ADNIV and neurodegenerative diseases." (PMID 29245980, 2017). "Importantly, the specific intracellular targeting of antibody fragments blocking activation of CAPN5 act as inhibitors of CAPN5 functions in neural like cells, thus, our data provides a novel potential tool for therapy in CAPN5-mediated ADNIV or neurodegenerative diseases." (PMID 29245980, 2017).
neurodevelopmental disorder (1 paper, 2025). A behavioral and cognitive disorder with onset during the developmental period that involves impaired or aberrant development of intellectual, motor, or social functions. "Many CAPN5 substrate candidates identified in this study harbor genetic variants that cause human diseases including several neurodevelopmental disorders." (PMID 40650235, 2025).
CAPN5 also shares sentences with these, for which no sentence is quoted: proliferative vitreoretinopathy (3 papers); diabetic retinopathy (2); retinitis pigmentosa (2); age-related macular degeneration (1); albinism (1); glaucoma (1); glioblastoma (1); Huntington disease (1); Hypercholesterolemia (1); leiomyosarcoma (1); neuropathy (1); pancreatic cancer (1); polycystic ovary syndrome (1); posterior uveitis (1); proliferative diabetic retinopathy (1); prostate carcinoma (1); Retinal atrophy (1); Retinal neovascularization (1); rhegmatogenous retinal detachment (1); viral infection (1); Vitreoretinopathy (1).